UHRF1 (ubiquitin like with PHD and ring finger domains 1)
Description:
E3 ubiquitin-protein ligase that acts as a key epigenetic regulator by bridging DNA methylation and chromatin modification. Plays a key role in DNA methylation inheritance by promoting recruitment of DNMT1 to hemimethylated DNA and ensure faithful propagation of the DNA methylation patterns through DNA replication. Acts both as a histone reader and writer: specifically recognizes and binds (1) hemimethylated DNA at replication forks and (2) histone H3 trimethylated at 'Lys-9' and unmethylated at 'Arg-2' (H3K9me3 and H3R2me0, respectively), thereby activating its E3 ubiquitin-protein ligase activity. UHRF1 then mediates histone H3 'Lys-18' monoubiquitination (H3K18ub), a docking site for DNMT1, leading to DNMT1 recruitment and replication-coupled DNA methylation maintenance. Also mediates histone H3 'Lys-14' and 'Lys-23' ubiquitination (H3K14ub and H3K23ub) at lower level. Histone ubiquitin ligase activity also stimulates the methyltransferase activity of SUV39H1 and/or SUV39H2, promoting accumulation of H3K9me3 histone mark to reinformce heterochromatin state. Enriched in pericentric heterochromatin where it recruits different chromatin modifiers required for this chromatin replication. Also localizes to euchromatic regions where it negatively regulates transcription possibly by impacting DNA methylation and histone modifications. Plays a role in DNA repair by cooperating with UHRF2 to ensure recruitment of FANCD2 to interstrand cross-links (ICLs) leading to FANCD2 activation. Also ubiquitinates non-histone proteins, such as histone H3, KIF11 and PML. Acts as a critical player of proper spindle architecture by catalyzing the 'Lys-63'-linked ubiquitination of KIF11, thereby controlling KIF11 localization on the spindle.
Synonyms: HuNp95; hNp95; hUHRF1; ICBP90; NP95; RNF106; FLJ21925; TDRD22
Tractability: Small molecule: a structure with a bound ligand is known; a high-quality ligand is known; it has a high-quality binding pocket. PROTAC: UniProt records ubiquitination sites on it; ubiquitination databases record sites on it; its protein half-life has been measured; a small molecule that binds it is known.
Target class: Plant homeodomain; Epigenetic regulator; Reader
Gene: Protein-coding gene on chromosome 19 (4,903,080 to 4,962,154, forward strand). Ensembl gene ENSG00000276043.
Subcellular location: Nucleus; Chromosome
Subcellular location (Human Protein Atlas): Nucleoplasm
Pathways (Reactome):
Developmental Biology: Chromatin modifications during the maternal to zygotic transition (MZT)
Gene expression (Transcription): DNA methylation
Gene Ontology:
Molecular function: cis-regulatory region sequence-specific DNA binding; hemi-methylated DNA-binding; histone binding; histone H3 ubiquitin ligase activity; histone H3K14 ubiquitin ligase activity; histone H3K18 ubiquitin ligase activity; histone H3K23 ubiquitin ligase activity; histone H3K9me2/3 reader activity; methyl-CpG binding; nucleic acid binding; protein binding; ubiquitin protein ligase activity; ubiquitin-protein transferase activity; zinc ion binding; DNA damage sensor activity; identical protein binding; histone H3 reader activity
Biological process: chromosomal DNA methylation maintenance following DNA replication; heterochromatin formation; mitotic spindle assembly; negative regulation of gene expression via chromosomal CpG island methylation; negative regulation of transcription by RNA polymerase II; positive regulation of protein metabolic process; positive regulation of transcription by RNA polymerase II; protein autoubiquitination; protein localization to chromatin; regulation of epithelial cell proliferation; ubiquitin-dependent protein catabolic process; DNA damage response; double-strand break repair via homologous recombination; epigenetic regulation of gene expression; homologous recombination; protein ubiquitination; response to stress
Cellular component: chromatin; chromosome; euchromatin; heterochromatin; nucleoplasm; nucleus; replication fork; nuclear matrix; spindle
Genetic constraint (gnomAD): Loss-of-function variants: 9 observed, 91.65 expected, observed/expected ratio (o/e) 0.0982, 90% interval 0.058 to 0.17. The upper end of that interval is the gene's LOEUF score, 0.17, which puts it in group 1 of 6, group 1 being the genes least tolerant of losing a copy. Missense variants: 610 observed, 1,075.4 expected, observed/expected ratio (o/e) 0.57, 90% interval 0.53 to 0.61. Synonymous variants: 446 observed, 450.25 expected, observed/expected ratio (o/e) 0.99, 90% interval 0.92 to 1.07.
Homologues: Orthologues: chimpanzee UHRF1 (99% identical), macaque UHRF1 (98% identical), dog UHRF1 (89% identical), guinea pig UHRF1 (84% identical), pig UHRF1 (84% identical), rat Uhrf1 (75% identical), mouse Uhrf1 (74% identical), tropical clawed frog uhrf1 (68% identical), zebrafish uhrf1 (67% identical). Paralogues in human: UHRF2 (55% identical), SHISA5 (8% identical).
Diseases named in the same sentence as UHRF1 in open-access papers:
UHRF1 is named in the same sentence as 146 diseases in open-access papers, as found by Europe PMC text mining. Sharing a sentence is not in itself a finding about the gene and the disease. The quoted sentences say what the papers report.
colorectal cancer (36 papers, 2011 to 2025). A primary or metastatic malignant neoplasm that affects the colon or rectum. "Promoter hypermethylation of the PPARG gene by ubiquitin-like, containing PHD and RING finger domains, 1 (UHRF1) are associated with poor prognosis in colorectal cancer." (PMID 39195246, 2024). "It has been reported that increased UHRF1 is associated with cellular proliferation and has observed in various types of cancers such as colorectal cancer." (PMID 28241740, 2017). "Depletion of UHRF1 led to a visible loss in cell number, as observed in non‐small cell lung cancer 25, colorectal cancer 23 and prostate cancer." (PMID 26497117, 2016). "In agreement with our previous studies, we propose two mechanisms targeting UHRF1 and underlying the antitumoral activities of RWPs in colorectal cancer." (PMID 21496237, 2011). "We recently generated degron alleles of DNMT1 and UHRF1 in colorectal cancer cells." (PMID 40595593, 2025). "However, the regulatory mechanism underlying UHRF1 expression in colorectal cancer (CRC) is still unclear." (PMID 31803739, 2019). "We generated colorectal cancer cell lines in which the endogenous copies of UHRF1 and/or DNMT1 are tagged with fluorescent markers as well as degron tags, allowing for their rapid and controlled depletion." (PMID 38580649, 2024). "We generate and validate degron alleles of UHRF1 and/or DNMT1 in human colorectal cancer cell lines." (PMID 38580649, 2024). "We previously showed that UHRF1 supports the growth and metastasis of human colorectal cancer (CRC) through repression of TSG expression." (PMID 39607687, 2024). "Studies with mouse embryonic stem cells (mESCs) and colorectal cancer cells showed that knockdown of UHRF1 induced global DNA hypomethylation." (PMID 37573395, 2023). "Luteolin treatment in colorectal cancer cells not only down-regulates the levels of UHRF1 and DNMT1, but also activates the re-expression of TSG p16INK4A." (PMID 37630248, 2023). "UHRF1 is a recognized oncogene, which is highly expressed in many tumors, including ovarian cancer, breast cancer, gastric cancer, and colorectal cancer." (PMID 35211429, 2022). "In colorectal cancer, UHRF1-mediated methylation of a peroxisome proliferator-activated receptor (PPARγ) was shown to be a key determinant of disease progression." (PMID 36077796, 2022). "miR-202 was shown to inhibit cell proliferation and invasion of colorectal cancer and bladder cancer by targeting UHRF1 and EGFR respectively." (PMID 33002044, 2020). "In this study, we examined the involvement of UHRF1 in aberrant DNA methylation and gene silencing in colorectal cancer (CRC)." (PMID 31064417, 2019). "HCT116 colorectal cancer cell lines were simultaneously transduced with shRNA against UHRF1 and rescued with either NDI1 (unrelated yeast control gene), UHRF1 WT (positive control), UHRF1 SUVH5 finger, or UHRF1 N489A." (PMID 31481468, 2019). "To address this issue, we comprehensively analyzed the effect of UHRF1 depletion on DNA methylation and gene expression in colorectal cancer (CRC) cells." (PMID 31064417, 2019). "Immunohistochemistry and microarray analysis of various tissues from cancer patients also supports UHRF1 overexpression in several cancer types, such as lung, breast, gastric, prostate and colorectal carcinomas." (PMID 29899856, 2018). "UHRF1 overexpression in colorectal cancer has been observed in several studies and is considered to be involved in promoter hypermethylation mediated repression of TSGs." (PMID 28881702, 2017). "Another study in which 231 colorectal cancer tissues and 40 adenoma specimens were analyzed for UHRF1 levels reported similar results." (PMID 28881702, 2017). "In previous studies of miRNA regulation of UHRF1 in cancers, UHRF1 was regulated by miR-146a/146b in gastric cancer, miR-9 in colorectal cancer, and miR-124 in BC." (PMID 27072587, 2016). "Inhibition of UHRF1 using siRNA decreased cellular proliferation and migration in colorectal cancer cell lines." (PMID 27507047, 2016).
colorectal cancer (continued). "UHRF1 was also identified from our literature search as a clinically relevant marker of lymph node metastatic capacity, in this case in colorectal carcinoma samples." (PMID 23118918, 2012). "It was previously shown that UHRF1 negatively regulates PPARγ and increases proliferation, migration, and clonal formation in colorectal cancer cells lines, and the molecular mechanism revealed that UHRF1 recruits PPARγ promoter and accelerates DNA methylation and repressive histone modification." (PMID 31428652, 2019). "Upregulation of UHRF1 may serve as a biomarker for a variety of cancers; including breast, gastric, prostate, lung and colorectal carcinoma." (PMID 29899856, 2018). "Indeed, immunohistochemistry showed high expression of UHRF1 in the nucleus of 65.8% (152/231) colorectal cancer tissues and of 87.5% (35/40) adenoma samples while little or no expression was found in normal colonic mucosa." (PMID 28881702, 2017). "Moreover, it has recently been demonstrated that UHRF1 down-regulation inhibits cell growth and induces apoptosis of colorectal cancer through p16INK4A up-regulation." (PMID 23688286, 2013). "In agreement with this hypothesis, UHRF1 down-regulation has been shown to inhibit cell growth and induces apoptosis of colorectal cancer through p16INK4A up-regulation." (PMID 23688286, 2013). "UHRF1 protein expression was determined in 144 clinical colorectal carcinoma samples." (PMID 23118918, 2012). "In this case, we treated the engineered HCT116 human colorectal carcinoma cells with dox for 2 weeks (to generate hypomethylated genomes), terminated the dox treatment and then monitored DNA methylation recovery for 2 weeks as UHRF1 or DNMT1 expression was restored." (PMID 39607687, 2024). "Indeed, high levels of UHRF1 were observed in different types of cancers, including breast cancer, cervical cancer, colorectal cancer, prostate cancer, lung cancer, ovarian cancer, gall bladder cancer, retinoblastoma, osteosarcoma, and hepatocellular carcinoma." (PMID 37630248, 2023). "Thus, targeting UHRF1 by natural compounds could be an interesting way to prevent and/or to treat colorectal cancers." (PMID 21496237, 2011). "Analysis of larger colorectal cancer datasets further revealed consistent upregulation of EZH2, EED, and UHRF1 in BRAF-mutant CRCs compared to BRAF-wildtype tumors, reinforcing the broader relevance of these findings." (PMID 40678543, 2025). "To enable the comparative study of DNA methylation maintenance dynamics supported by UHRF1 and DNMT1, we engineered HCT116 human colorectal carcinoma cells to express dox-inducible shRNAs targeting the UHRF1 or DNMT1 3′UTRs." (PMID 39607687, 2024). "Methylation-driven tumorigenic phenotypes have been best described in colorectal cancer (CRC) and prior studies have also demonstrated that UHRF1 plays a role in mediating these effects in CRC21,30,45." (PMID 37407562, 2023). "We next tested if 2i also regulates UHRF1 and DNMT1 in HCT116, a human colorectal carcinoma cell line." (PMID 30696879, 2019). "UHRF1 coordinates PPARG (peroxisome proliferator-activated receptor γ) epigenetic silencing and mediates colorectal cancer progression." (PMID 25272010, 2014). "Human UHRF1 (also known as ICBP90) was initially discovered as a regulator of TopoIIalpha, which is an oncogene that is overexpressed in a variety of solid and hematological tumors, including hepatocellular carcinoma, lung cancer, and colorectal cancer." (PMID 39267107, 2024). "To determine whether UHRF2 and UHRF1 also negatively regulate DNMT3A in human cancer cell lines, we knocked down UHRF2 or UHRF1 in cervical cancer HeLa and colorectal cancer HCT116 cells by lentiviral-mediated shRNA infection." (PMID 27462454, 2016). "Using luteolin to target calpain, UHRF1, and DNMT1 may help prevent or treat colorectal cancer." (PMID 35327559, 2022).
hepatocellular carcinoma (31 papers, 2015 to 2024). A malignant tumor that arises from hepatocytes. "For instance, overexpression of UHRF1 causes genome-wide DNA hypomethylation in hepatocellular carcinoma and esophageal squamous cell carcinoma, while UHRF1 has only minor effects on DNA methylation in retinoblastoma." (PMID 31064417, 2019). "In this current study, we further investigated the role of UHRF1 deficiency in human hepatocellular carcinoma cells." (PMID 28584306, 2017). "Previous studies have suggested that regulation of tumor immune escape via the RP11-424C20.2/UHRF1 axis plays a different role in the progression of hepatocellular carcinoma (LIHC) and thymoma (THYM) and is associated with IFN-γ-mediated CLTA-4 and PD-L1 pathways." (PMID 35656341, 2022). "This highlights UHRF1’s potential as a therapeutic target, offering new hope for enhanced treatment outcomes in hepatocellular carcinoma cases." (PMID 38813086, 2024). "A study described that tumor-derived exosomal circulating UHRF1 promotes NK cell exhaustion in hepatocellular carcinoma." (PMID 37460953, 2023). "Researchers have found that forced UHRF1 expression can promote tumorigenesis and the progression of hepatocellular carcinoma (HCC)." (PMID 35464451, 2022). "Survival analyses with the univariate Cox regression model revealed their crucial roles in the patient outcomes, of these, DNMT3A, UHRF1, DNMT1, DNMT3B and TET1 the risk factors for hepatocellular carcinoma." (PMID 35771147, 2022). "Other studies have suggested that UHRF1 overexpression (in hepatocellular carcinoma), and PIWI protein repression (in testicular cancer) contribute to GDHO." (PMID 32213861, 2020). "Inhibition of UHRF1 expression reduced cell growth in hepatoma cell lines via cyclin E/CDK2/p21 axis." (PMID 32528965, 2020). "Knockdown of UHRF1, both in vitro and in vivo, inhibited cancer progression in hepatocellular carcinoma by inducing G2/M arrest during cell cycle." (PMID 29899856, 2018). "On a different note, downregulation of UHRF1 have also been reported to enhance the migratory and invasive properties of hepatocellular carcinoma and contributes to the development of cancer stem-like cells." (PMID 29899856, 2018). "In this study, we observed that hypoxia-induced downregulation of UHRF1 contributes to the induction of the epithelial-mesenchymal transition (EMT) in hepatocellular carcinoma cells." (PMID 28584306, 2017). "In the context of tumorigenesis, a recent study reported that transgenic UHRF1 overexpression in normal zebrafish hepatocytes induces DNA hypomethylation, and a subset of the transgenic fish develop hepatocellular carcinoma." (PMID 28467809, 2017). "A recent study reported that transgenic overexpression of UHRF1 in zebrafish hepatocytes can drive hepatocellular carcinoma by inducing global DNA hypomethylation and subsequently bypassing senescence." (PMID 28467809, 2017). "UHRF1 and Sp1 mRNA levels were also increased in hepatocellular carcinoma HCCs patient tissues compared to adjacent normal tissues in parallel with a decrease in the expression of TRα1 and p21." (PMID 27839516, 2016). "In this context, it has been shown that T3 negatively regulates the expression of UHRF1 in hepatoma cell line, which highly overexpresses TRα1." (PMID 27839516, 2016). "One such gene that stands out is UHRF1 which has been shown to act as an oncogene that drives DNA hypomethylation in hepatocellular carcinoma." (PMID 25889361, 2015). "Moreover, targeting PHD finger-containing protein UHRF1 markedly slows the advancement of hepatocellular carcinoma." (PMID 38813086, 2024).
hepatocellular carcinoma (continued). "A large number of studies have shown that the differential expression of UHRF1 is highly expressed in a series of human tumors such as breast cancer, cervical squamous cell carcinoma, esophageal squamous cell carcinoma, hepatocellular carcinoma, and colon cancer." (PMID 35656341, 2022). "UHRF1 is expressed at a constant high level in cancer cells, including breast cancer, lung cancer, bladder cancer, laryngeal squamous cell carcinoma, hepatocellular carcinoma, and esophageal squamous cell carcinoma." (PMID 30174788, 2018). "UHRF1 thus can be a potential prognostic biomarker for hepatocellular carcinoma." (PMID 29899856, 2018). "In addition, E2F8 was reported to transcriptionally upregulate cyclin D1 in hepatocellular carcinoma, and UHRF1 in lung cancer." (PMID 26992224, 2016). "For example, UHRF1 in hepatocellular carcinoma (HCC) 19, CXCL11 in colorectal cancer (CRC) 20, AFF3 in GC 21, and so on." (PMID 38706903, 2024). "UHRF1 and SNX27 were host genes of exosomal circRNA that showed more than two-fold difference in expression in hepatocellular carcinoma." (PMID 34249673, 2021). "Among them, ubiquitin-like with PHD and ring finger domains 1 (UHRF1) and sorting nexin 27 (SNX27) with a fold change >2, revealing significantly high expression in hepatocellular carcinoma." (PMID 34249673, 2021). "An elevated level of UHRF1 expression is observed in hepatocellular carcinoma (HCC)." (PMID 29899856, 2018). "In hepatocellular carcinoma (HCC), overexpression of UHRF1 facilitates DNA hypomethylation." (PMID 29899856, 2018). "Reduced levels of UHRF1 have been shown to regulate the ferroptosis-related gene CDO1 by epigenetic mechanisms, thus up-regulating the level of CDO1 and increasing the sensitivity of hepatocellular carcinoma and cervical cancer cells to ferroptosis." (PMID 37406020, 2023). "In contrast to UHRF1, UHRF2 exhibits tumor-suppressor gene capacities, but an ability to favor tumor progression cannot be excluded, at least in certain types of cancer, such as hepatocellular carcinoma or intestinal tumorigenesis." (PMID 37630248, 2023). "For example, in a study, while UHRF1 downregulation inhibited tumor growth in hepatocellular carcinoma (HCC) cell lines, it did not trigger apoptosis." (PMID 39051184, 2024). "Ubiquitin-like with plant homeodomain and ring finger domains, 1 (UHRF1) is overexpressed in a variety of tumor tissues and is negatively correlated with prognosis of patients with cancers, yet so far, a comprehensive study of UHRF1 in hepatocellular carcinoma (HCC) has not been conducted." (PMID 28060737, 2017).